RHOA (ras homolog family member A)
Diseases named in the same sentence as RHOA in open-access papers (continued):
Sharing a sentence is not in itself a finding about the gene and the disease.
cancer (continued). "RhoA mediates the cell motility of many diverse types of cancer as indicated by its regulation of cytoskeletal organization and gene expression." (PMID 34528373, 2021). "ANLN, a homolog of anillin whose stability and nuclear localization are regulated by the PI3K/AKT pathway, can bind to and activate RHOA, thus promoting cancer growth and development." (PMID 34746138, 2021). "Surprisingly, a comprehensive analysis of 14 major carcinomas across 6586 patients revealed that epithelial tumors frequently harbor putative heterozygous deletions of RHOA, SLK, STK10, and ERM." (PMID 34635648, 2021). "Recently, RHOA is frequently reported as an oncogenic gene implicating in the initiation and progression of malignant tumors via exacerbating cell migration and invasion." (PMID 31820783, 2020). "RHOA has been reported to be involved in multiple human diseases, including cardiovascular disease and cancer." (PMID 33156843, 2020). "Low doses of berberine derived from Coptidis rhizome inhibited Rho GTPase including RhoA, Cdc42, and Rac1 and cell migration in different human cancer cells." (PMID 32443784, 2020). "Small Rho GTPases including RhoA, Rac1, and Cdc42 are well known to regulate cell migration, and overexpression of these molecules in human cancer correlates with cancer progression." (PMID 32802134, 2020). "The most studied Rho GTPases in oncogynecology are RhoA, RhoC, Rac1, and Cdc42, which show higher expression correlating with the advancement of the cancer." (PMID 32443784, 2020). "Exosomal circ-133 derived from hypoxic cells delivered into normoxic cells and promoted cancer metastasis by acting on miR-133a/GEF-H1/RhoA axis." (PMID 32724467, 2020). "Previous studies have demonstrated that GEF-H1/RhoA is involved in the regulation of cytoskeleton components and plays a key role in cancer invasion and metastasis 21-23." (PMID 32724467, 2020). "What is more, overexpression of RhoA or ROCK1 has contributed to malignant phenotype of cancers, such as ESCC." (PMID 32546278, 2020). "The recent efforts in next-generation sequencing have revealed that Rho GTPases are mutated in a variety of cancers, and recurrent mutations in RAC1 and RHOA have been identified." (PMID 32526908, 2020). "RhoA activity is deregulated in various human cancers, and seems to be involved in almost all stages of cancer progression." (PMID 32392742, 2020). "This Ran–RhoA signaling complex seems to be a possible molecular target for controlling cancer metastasis." (PMID 32443784, 2020). "Remarkably, hydrogen peroxide induces Tyr42 phosphorylation of RhoA, leading to NF-κB activation in cancer cell and tumor progression." (PMID 32046944, 2020). "Recently, we found that hydrogen peroxide up-regulates p-Tyr42 RhoA, leading to NF-κB activation and cancer cell proliferation." (PMID 32046944, 2020). "To conclude, hypoxic exosomal circ-133 can promote cancer metastasis by GEF-H1/RhoA axis and is expected to be a potential therapeutic target." (PMID 32724467, 2020). "Then it was verified both in vitro and in vivo that exosomal circ-133 derived from hypoxic cells transported into normoxic cells and regulated the E-cadherin membrane distribution, promoting cancer metastasis via miR-133a/GEF-H1/RhoA axis." (PMID 32724467, 2020). "This suggests that, in addition to the tight spatiotemporal control of RhoC activity, co-ordinated activation of RhoA at different stages of the invadopodium lifecycle is required for efficient cancer cell invasion." (PMID 32309283, 2020). "RHOA is recognized as driver gene in DLBCL and RAC1 is recurrently mutated or upregulated in cancers." (PMID 32349449, 2020). "In cancer cells, p120catenin has also been reported to activate Rac1, which, in combination with reduced substrate adhesion due to RhoA inhibition, promotes cancer cell invasion." (PMID 32443411, 2020).
cancer (continued). "Among them, RhoA has been identified to play a central role in regulating the actin organization, in acto-myosin contraction, in cancer cell adhesion and migration." (PMID 32770034, 2020). "Pathways related to nervous system development (FDR = 5.8 × 10−8) were enriched for the PID-N genes ASCL1, CTNNB1, ID2, SUFU, and TERT that have known roles in cancer, complementing the PID-C genes NOTCH1, PTEN, and RHOA that also have known cancer roles." (PMID 32024854, 2020). "Several members of the Rho family of GTPases have been in the context of cancer angiogenesis, migration, and invasion, most notably RhoA, RhoB, RhoC, RhoG, Rac1, and Cdc42." (PMID 32089990, 2020). "In endothelial cells, ARHGAP18 was shown to act preferentially on RhoC, whereas in cancer cells it shows specificity mainly for RhoA." (PMID 33092266, 2020). "This activation is triggered by the binding of cancer cells to the extracellular matrix (ECM) which results in a RhoA-dependent actin recruitment and the formation of nascent adhesions and eventually focal complexes." (PMID 32377503, 2020). "Here, we show that specific activation of GPER inhibits EMT, mechanotransduction and cell contractility in cancer cells via the GTPase Ras homolog family member A (RhoA)." (PMID 31991740, 2020). "Knockdown of RhoA expression significantly suppressed cancer cell growth and tumorigenesis and enhanced the chemosensitivity of cancer cells to treatment with Adriamycin and 5-fluorouracil." (PMID 33126743, 2020). "Since RhoA activity is essential for cancer cell migration and metastasis, we investigated the role of BNIP-2 in MDA-MB-231 cell migration." (PMID 32789168, 2020). "Scholars have reported numerous lncRNAs involved in regulating human cancer cell growth and metastasis through the modulation of the RhoA pathway, including SNHG5, LOC554202, and MALAT1." (PMID 33126743, 2020). "Mechanistically, StarD13 effects on cancer cell motility and adhesion in vitro were mediated by its RhoA GAP activity on RhoA and its indirect Rac1 regulation." (PMID 32900380, 2020). "Cancer cell invasion plasticity is known to be controlled by shifting the balance in the mutually antagonistic regulation of Rac1 and RhoA." (PMID 32872349, 2020). "Rho GTPases (RhoA, Rac1, and Cdc42) have been studied in connection with breast carcinogenesis, as well as in connection with other cancers, for many years." (PMID 32443784, 2020). "Studies have demonstrated that microRNA and lncRNA modulate the growth and invasion properties of human cancer cells through the fine-tuning of RhoA/ROCK signaling." (PMID 33126743, 2020). "RhoA was abnormally expressed in various human cancers and involved in the occurrence, development, invasion, and metastasis." (PMID 33336057, 2020). "Despite these difficulties, some promising RhoA inhibitors have already been developed to be used in cancer treatment." (PMID 30884855, 2019). "As previously shown in cancer cells, ephrin-A5 increased RhoA activity in hippocampal neurons, whereas DAPT significantly increased and caused a synergistic effect on RhoA activation." (PMID 31577226, 2019). "The RHO GTPase enzyme family, including RHOA, Rac, and cdc42, is essential for diverse biological processes, including cell morphology phenotypes, cell polarity, and cell migration, in diverse cancer types." (PMID 31156701, 2019). "Matrine treatment retarded the cancer associated signaling transduction by decreasing the phosphorylation levels of ERK1/2, MEK1/2, PI3K, Akt, mTOR, FAK, RhoA, VEGFR2, and Tie2 in vitro and in vivo." (PMID 31601793, 2019). "Like most other GTPases, RhoA and their activating proteins, guanine nucleotide exchange factors (GEFs), are commonly believed to be pro-proliferative and act as cancer oncogenes." (PMID 31705019, 2019). "Cytoplasmic p120ctn was found to interact with Rho GTPases RhoA, Rac1 and Cdc42 to influence cancer cell motility and metastasis." (PMID 30795761, 2019).
cancer (continued). "Cdc42 and RhoA have long been known to promote the trafficking of metalloproteinases to the tips of invadopodia to promote cancer cell metastasis by driving an interaction between IQGAP with the exocyst complex." (PMID 30292078, 2019). "Multiple cancer-associated proteins, including several that have since been shown by others to regulate YAP or TAZ (RhoA, Cdc42, Ras, and phosphoinositide 3-kinase (PI3K)) (28, –, 32), increased YAP/TAZ transcriptional activity." (PMID 30559289, 2019). "Many studies have shown that RhoA/ROCK-mediated cytoskeletal regulation plays a key role in cancer metastasis." (PMID 30678736, 2019). "The present results suggest that the EPHB6 mutation and its downstream EPHA2/JNK/CDH11/RhoA/FAK signaling axis are novel diagnostic and therapeutic targets for overcoming paclitaxel resistance in cancer patients." (PMID 31160603, 2019). "Platelets promote cancer metastasis also depending on the activating of YAP1 signaling through the RhoA / MYPT-PP1 pathway." (PMID 30646853, 2019). "It is therefore likely that the increased co-expression of CXCR4 and CCR5 in RhoA knockdown cancer cells facilitates the recruitment of CXCL12/CCL5 secreting CAFs and later the TAMs into the TME." (PMID 31705019, 2019). "Recent studies have suggested that RhoA is one of the genes that is most frequently overexpressed in various cancer cells and is involved in cell division processes, and RhoA promotes HCC growth through the RhoA/F-actin/Hippo-YAP signaling axis." (PMID 31339860, 2019). "Recently, roles for RHOA in cell motility have been identified, in many diverse types of cancer, but RHOA’s clinical significance (including therapeutic feasibility), to GC, one of the most lethal cancers in East Asia, remains little known." (PMID 31156701, 2019). "Taken together, our study suggest that RhoA suppresses the cancer cells’ initial steps of local invasion into SLNs, and subsequent intravasation into LN blood vasculature while has no observable role in the later steps of the metastasis cascade." (PMID 31705019, 2019). "The expression of CCR5, the cognate receptor for CCL5 was likewise found to be upregulated in RhoA knockdown 4T1 cancer cells." (PMID 31705019, 2019). "The inactivation of RHOA promoted cancer cells invasion and de-differentiation by Wnt signaling pathway." (PMID 31506480, 2019). "RhoA is generally overexpressed in cancer and is a key GTPase required for cell migration by reorganization of the actin cytoskeleton in temporal and spatial fashion." (PMID 31332286, 2019). "In this case, RhoGDI1 activates the PI3K and MAPK pathway by increasing RhoA expression, thereby promoting cancer cell proliferation and migration." (PMID 31492019, 2019). "Using these, we assigned RHOA functions, from the 47 identified publications, according to relevance to the 10 cancer hallmarks." (PMID 31156701, 2019). "On the contrary, bioluminescent imaging of mice at 29 days post-implantation revealed possible distant metastases in mice implanted with the highest RhoA knockdown (shRhoA 32) 4T1 cells showing a dose-dependent effect of RhoA knockdown on cancer metastasis." (PMID 31705019, 2019). "In different cancers, activation of RhoA has been shown to promote cell migration and invasion by reorganization of the cytoskeleton." (PMID 31569361, 2019). "Through the analysis of copy number alteration of PM samples, we found that there were significant deletions in many genomic regions of PM samples, involving many cancer genes and immune related genes (such as B2M, RHOA, IFNE, JAK1/2, etc.)." (PMID 31570735, 2019). "RhoA GTPase has several downstream effectors and some of them reported to have opposing effects on cancer cells invasion." (PMID 31705019, 2019). "Knockdown of RhoA expression increases CCR5 and CXCR4 transcripts in 4T1 cancer cells suggesting a possible transcription-regulatory function of RhoA." (PMID 31705019, 2019).
cancer (continued). "RhoA or RAC1 are mutated in a few cancers, but in most cancers, expression levels and/or activity of Rho GTPases is altered via a number of regulatory mechanisms." (PMID 31027363, 2019). "It is possible that reduced RhoA expression promotes cancer cell dissemination into sentinel lymph nodes by modulating this dynamic interplay." (PMID 31705019, 2019). "Matrine administration obviously decreased the phosphorylation levels of ERK1/2, MEK1/2, PI3K, Akt, mTOR, FAK, RhoA, VEGFR2 and Tie2 in vivo, and then accordingly retarded cancer associated signaling transduction." (PMID 31601793, 2019). "In EOC, cytoplasmic p120ctn regulates the activation of the Rho GTPases RhoA, Rac1 and Cdc42, which are known to be essential modulators for cell migration and invasion and consequently promoting cancer cell motility and invasion." (PMID 30795761, 2019). "Recently, it was shown that RHOA can be targeted by small molecule inhibitors, in cancer, implicating it as a potential druggable target." (PMID 31156701, 2019). "We initially examined both the mRNA and protein expression patterns of RhoA in normal human organs, common cancer types and cell lines using an HPA web-based tool." (PMID 31339860, 2019). "The lncRNA AFAP1-AS1 is involved in many types of malignant tumors and upregulates RhoA expression to promote proliferation and metastasis of HCC." (PMID 31248165, 2019). "Apparently, the enhanced CXCR4 expression is an autonomous effect of the downregulation of RhoA expression in 4T1 cancer cells." (PMID 31705019, 2019). "In summary, although existing evidence demonstrates the feasibility of employment of RHOA as both a biomarker candidate and druggable target, further investigation of its application to GC (and other cancer) therapy, is urgently needed." (PMID 31156701, 2019). "RhoA, one of Rho GTPase family members, is an intracellular molecular switch that transduces signals in various cancers and promotes actin polymerization." (PMID 30886866, 2019). "Cancer cells display at least two distinct modes of single-cell migration, which are regulated by Rho family proteins (including RhoA, Rac1 and Cdc42)." (PMID 29535813, 2018). "The amazing results of pre-clinical studies indicate that RhoA and RhoC have different clinical roles in regulating transcriptional factors, invasion and metastasis of cancer cells in multiple cancers and are overexpressed in various solid tumors." (PMID 29861465, 2018). "Independently of IGF-1, the crosstalk between CAFs and BC cells also increased the expression of PAI-1 in MDA-MB-231 cells, while geodin-inhibition of PAI-1 reduced RhoA activity in cancer cells, cancer cell scattering and invasion." (PMID 29535813, 2018). "Here, we provide evidence that hypoxia-induced upregulation of supervillin promotes cancer cell migration and invasion while increasing the activation of RhoA." (PMID 29954442, 2018). "Both IGF1 and PAI-1 activate RhoA/ROCK signaling in cancer cells, which increases cell scattering and invasion." (PMID 29535813, 2018). "Both RhoA and NFkB are involved in the regulation of genes involved in diverse processes in cancer including invasion and metastasis." (PMID 29541406, 2018). "CLDN18 fusions are expected to inhibit the RHOA pathway, and in some contexts, RHOA inhibition promotes cancer cell invasion in vitro." (PMID 30034621, 2018). "To study amoeboid cancer cell behaviour in 3D collagen, we induced expression of constitutively active RhoA in HT1080 cells, which resulted in the gain of the amoeboid phenotype." (PMID 30104699, 2018). "Because RhoA-dependent remodeling / contraction of the ECM by CAFs can promote cancer cell migration we also used shRNA constructs to knockdown the expression of RhoA in CAFs." (PMID 29535813, 2018). "RhoA activation is an important regulator in this event, and thus has an important role in Eph/ephrin control of cancer cell migration." (PMID 29059157, 2018).
cancer (continued). "The Ras homolog gene family, member A (RhoA) GTPase is crucial for cancer metastasis, and RhoA transcription is regulated by the Skp2 complex." (PMID 29743060, 2018). "To test if RBP4 induced cancer cell migration is RhoA/Rock1 dependent, we added Y-27632 to our RBP4 overexpression cells." (PMID 29642915, 2018). "Because of the several unique post-translational modifications that are distinct from RhoA and RhoC, RhoB is argued to be the most diverse protein of the Rho subgroup, a factor possibly contributing to its dualistic role in cancer." (PMID 29385717, 2018). "The increased expression of both IGF-1 and PAI-1 enhances RhoA signaling in cancer cells, which promotes cell scattering and invasion." (PMID 29535813, 2018). "This is the first demonstration that the activation of RhoA is induced by NRP1 alone in cancer cells, although RhoA in endothelial cells has been reported to be activated specifically by NRP1 through the Gq and PI3 kinase pathway for cell migration." (PMID 29659486, 2018). "First, we found that inhibition of RhoA/ROCK/myosin II pathway promoted the phagocytosis of cancer cells in vitro and in vivo." (PMID 29867097, 2018). "To confirm that CAFs promote cancer cell invasion by activating RhoA in MDA-MB-231 cells, we used shRNA interference to reduce the expression of RhoA in both cancer cells and CAFs." (PMID 29535813, 2018). "Knockdown of ephrinB1 in SW480 and Hs578T human cancer cell lines suppresses RhoA activation by EphB2-Fc." (PMID 29059157, 2018). "Despite the technique’s novelty, the roles of RhoA and RhoC are being searched for successful management of cancer for further advancement in the future." (PMID 29861465, 2018). "Metastatic cancer cell-derived exosomes export thrombin and activate the RhoA/Rock pathway in recipient cell, while PCC-derived exosomes play a role in increasing proliferation and migration and induce activation and profibrogenic in pancreatic stellate cell." (PMID 30326899, 2018). "Here, we show that the stimulation of ephrinB1 by EphB2-Fc promotes migration and invasion of cancer cells through RhoA activity." (PMID 29059157, 2018). "Together, both studies suggest that ECT2 and DLC1 frequently act together, but in opposite directions, in cancer to increase RhoA activity." (PMID 30278072, 2018). "RhoA and RhoC are the key drivers for cancer aggressiveness e.g., increased cellular proliferation and metastasis by activating several pathways that catalyze cell survival and proliferation." (PMID 29861465, 2018). "The crosstalk between CAFs and cancer cells activates RhoA/ROCK signaling in cancer cells, which is dependent on the secretion of IGF-1 by CAFs and PAI-1 upregulation in cancer cells." (PMID 29535813, 2018). "Previously, the small GTP-binding protein RhoA has been demonstrated to be involved in Cntn1-induced F-actin polymerization during cancer cell migration." (PMID 30515076, 2018). "It has been well-established in many studies that RhoA and RhoC are pro-tumorigenic in almost all cancer types." (PMID 29385717, 2018). "They showed that the fusion induced the epithelial mesenchymal transition and increased cancer invasiveness by inhibiting the RHOA pathway." (PMID 30034621, 2018). "Rac1 and RhoA/C contribute to metastasis by regulating separate types of invasive behavior in cancer cells, with Rac1 driving integrin-dependent, mesenchymal-type movement and RhoA/C driving integrin-independent, amoeboid movement." (PMID 29769144, 2018). "CDC42, RAC1, and RHOA are well characterized for actin reorganization, cancer invasion, and metastasis in various cancers but are still incompletely characterized in ESCC." (PMID 30327774, 2018). "RhoA/ROCK1 signaling has been shown to play an important role in cancer development and progression." (PMID 28841710, 2017).